RNU6-438P (RNA, U6 small nuclear 438, pseudogene)
Gene: Small nuclear RNA gene on chromosome 7 (34,297,496 to 34,297,598, reverse strand). Ensembl gene ENSG00000202431.
Homologues: Orthologues: chimpanzee U6 (97% identical), chimpanzee U6 (96% identical), macaque U6 (91% identical). Paralogues in human: RNU6-1145P (87% identical), RNU6-29P (86% identical), RNU6-38P (86% identical), RNU6-393P (86% identical), RNU6-39P (86% identical), RNU6-41P (86% identical), RNU6-1013P (85% identical), RNU6-16P (85% identical), RNU6-17P (85% identical), RNU6-18P (85% identical), RNU6-25P (85% identical), RNU6-44P (85% identical), and 1286 more.